INS (insulin)
Diseases named in the same sentence as INS in open-access papers (continued):
Sharing a sentence is not in itself a finding about the gene and the disease.
Hypoglycemia (continued). "We previously showed that lower hepatic glycogen content was associated with diminished glucagon and HGP responses to insulin-induced hypoglycemia in dogs, but the impact of liver glycogen content on islet hormone levels and HGP was not evaluated under euglycemic conditions." (PMID 37166980, 2023). "Higher doses of INI may temporarily increase circulating insulin and decrease blood glucose levels increasing the risk of hypoglycemia." (PMID 37379265, 2023). "It is possible that the reduced risk of hypoglycemia with insulin degludec might translate into a lower rate of CVDs." (PMID 36830610, 2023). "Moreover, inositol can reduce the need for insulin treatment and the risk of pregnancy-induced hypertensive disorders, preterm birth and neonatal hypoglycemia." (PMID 37836508, 2023). "However, the risk of hypoglycemia was higher among patients receiving insulin (relative risk 1.90, 95% CI 1.44 to 2.51)." (PMID 37468901, 2023). "This may be explained by the fact that the Control-IQ algorithm's dynamic basal modulation blunts the risk of hypoglycemia by effectively reducing the basal delivery in the hours after bolus insulin is administered." (PMID 37751154, 2023). "Insulin use is associated with an increased risk of hypoglycemia and weight gain." (PMID 37589043, 2023). "In addition, in the hypoglycemic group, the exposure of insulin, sulfonylurea and anti-depressants were significantly lower, which are known to increase the risk of hypoglycemia in DM patients." (PMID 37700268, 2023). "Therefore, the influence of GLP-1RAs on beta cell activation and deactivation phases, which probably play a significant role during the first phase of insulin secretion and can help assess the risk of hypoglycaemia, respectively, remain to be explored." (PMID 38292770, 2023). "This may be explained by the fact that in T1D patients with insulin omission/restriction, overtreatment to correct the hyperglycemic state may have contributed to the reduction of HbA1c levels by causing episodes of hypoglycemia." (PMID 37665472, 2023). "The stereoisomer myoinositol also reduced the risk of insulin need (RR = 0.29, CI: 0.13–0.68), preeclampsia or gestational hypertension (RR = 0.38, CI: 0.2–0.71), preterm birth (RR = 0.44, CI: 0.22–0.88), and neonatal hypoglycemia (RR = 0.12, CI: 0.03–0.55)." (PMID 37836508, 2023). "Conversely, the consumption of high glycemic index foods is associated with a further surge in glucose and insulin secretion, which may promote subsequent hypoglycemia." (PMID 37726785, 2023). "Lsd1 inactivation in β cells causes insulin hypersecretion and hypoglycemia." (PMID 36821378, 2023). "Moreover, eGFR less than 60 mL/min/1.73 m2, history of severe hypoglycemia, and insulin use were associated with severe hypoglycemia in an outpatient setting of a tertiary care hospital in Indonesia." (PMID 37758787, 2023). "Therefore, due to the loss of inhibitory control of GDH by mutations in GLUD1, insulin was secreted excessively under basal conditions as well as after protein meals, triggering hyperinsulinemia and hypoglycemia." (PMID 36721237, 2023). "However, the use of additional insulin doses for high-fat and protein meals was associated with a higher frequency of postprandial hypoglycemia." (PMID 40303273, 2023). "Long-acting insulin is avoided in patients with normal hemoglobin A1c values on admission, as long-acting insulin may cause difficulty with hypoglycemia when the inflammatory state resolves." (PMID 39600024, 2023). "Additionally, it was found that the patients are at risk of a hyperglycemia and a hypoglycemia event with an increased insulin requirement in the early stage of the disease." (PMID 36979645, 2023). "Although physical activity improves insulin sensitivity, it may be associated with an increased risk of hypoglycaemia in T1D patients, which can be reduced by advances in hybrid, closed-loop, artificial pancreas systems." (PMID 37065759, 2023).
Hypoglycemia (continued). "Congenital hyperinsulinism (CHI), also termed congenital hyperinsulinemic hypoglycemia (HH), is a disorder of glucose homeostasis due to dysregulated insulin secretion in the newborn or young infant and represents the most common cause of severe and persistent hypoglycemia in infancy and childhood." (PMID 37065762, 2023). "Bivariate analysis shows HbA1c less than 7%, subjects’ understanding of hypoglycemia symptoms, duration of T2DM more than 10 years, history of severe hypoglycemia, eGFR less than 60 mL/min/1.73 m2, use of sulfonylurea, and insulin use were associated with severe hypoglycemia." (PMID 37758787, 2023). "Importantly, GLP-1 RAs cause weight loss, reduce hypoglycaemia (compared with sulfonylureas and insulin), and are one of the most effective glucose-lowering medications, which are effects that we have not incorporated." (PMID 36404375, 2023). "Using insulin is likely to cause hypoglycemia and weight gain." (PMID 37242426, 2023). "T1D treatment consists of regulating BG levels using external insulin doses, whereas administering more insulin than needed might cause dangerous low BG levels (hypoglycemia)." (PMID 37835893, 2023). "The impact that these cyclic changes may have on blood glucose and insulin needs and the consequent risk of hypoglycemia during or after exercise are still unknown in this population." (PMID 36833469, 2023). "However, they found that the risk of hypoglycemia increased when this increased insulin dose was given as premeal regular insulin." (PMID 40303273, 2023). "Hypoglycaemia in CF may be caused by the mismatch between the rise in glucose and delayed insulin secretion from the beta cells." (PMID 37720541, 2023). "Therefore, the decision of choosing which type of insulin depends on the level of the associated risk of hypoglycaemia, the inconvenience of the injection frequency, accessibility and cost." (PMID 36837914, 2023). "The medications need to be specified and classified as they might be causative for hypoglycemia, insulin, for instance." (PMID 36923742, 2023). "Patients on insulin therapy may be initiated on tirzepatide therapy and cautiously tapered to minimize the risk of hypoglycemia." (PMID 37445623, 2023). "The abnormal metabolic and growth regulation that leads to intrauterine overgrowth may at the same time predispose to hypoglycemia and inappropriate insulin secretion in early postnatal life." (PMID 37065762, 2023). "Studies have speculated that insulin increased the risk of dementia due to hypoglycaemia, and other studies have confirmed that the frequency of hypoglycaemia is related to the duration of insulin use." (PMID 36804018, 2023). "Consequently, cornstarch results in lower insulin concentration, which is beneficial because high insulin concentration increases the risk of hypoglycemia and decreases the production of lactate and ketone bodies." (PMID 38370424, 2023). "However, patients with persistent endogenous insulin secretion demonstrate improved metabolic control, less hypoglycemia, and lower risk of diabetic ketoacidosis." (PMID 37226224, 2023). "However, one factor likely to oppose the effect of cold water on the risk of hypoglycemia in insulin-treated people with T1DM is the decrease in peripheral blood flow that normally accompanies cold exposure." (PMID 37942293, 2023). "Hypoglycaemia is an acute complication that is associated with overly low blood glucose levels (low blood sugar) and can become manifest mainly in the context of intensive insulin therapy." (PMID 37408713, 2023). "The most widely used route of administration in clinical practice is RI-in-PN, which has the advantages that the nutrient solution can be used with carbohydrates to intravenously deliver insulin at a stable rate, reduce the risk of hypoglycemia and decrease the time required for care." (PMID 37674887, 2023). "The authors hypothesized that elevated GLP-1 levels exacerbated the insulin spike and caused the consequent hypoglycemia." (PMID 37546099, 2023).
Hypoglycemia (continued). "Increasing the dose of insulin or Oral antidiabetes drugs may lead to further weight gain or increase the risk of hypoglycemia, causing poor glucose fluctuation." (PMID 37255975, 2023). "Insulin treatment is a major risk factor for hypoglycaemia in those with CKD, and less stringent HbA1c targets may be appropriate in individuals who experience hypoglycaemia in view of its association with increased mortality." (PMID 37152098, 2023). "Furthermore, around exercise the risk of hypoglycemia is higher due to increased insulin sensitivity, insulin absorption, glucose uptake in combination with an impaired glucagon secretion." (PMID 36755913, 2023). "Under conditions of impaired glucose tolerance, hypoglycemia may be caused by excessive postprandial insulin secretion." (PMID 38868726, 2023). "It has been shown that insulin pump treatment may be associated with behavior change and less hypoglycemia in comparison to MDIs." (PMID 37247225, 2023). "Either dietary approach in the trial could lower glucose levels, which could increase the risk of hypoglycemia among individuals using glucose-lowering medications, such as sulfonylureas or insulin, unless appropriate medication adjustments are made." (PMID 37475033, 2023). "Sometimes, tumor cells secrete insulin or insulin-like substances and cause hypoglycemia attacks." (PMID 37265904, 2023). "Metformin may be particularly useful in women with gestational diabetes at high risk for neonatal hypoglycemia, women who want to limit maternal and fetal weight gain, and women with an inability to afford or use insulin safely." (PMID 36593391, 2023). "This may be due to the high glycemic index (GI) foods that may lead to increased hunger in the middle of the postprandial period due to insulin‐induced hypoglycemia thus, causing prolonged and persistent hyperphagia." (PMID 37970433, 2023). "Therefore, all patients on insulin therapy and those who carry a high risk of hypoglycemia, including those with renal insufficiency should be closely monitored with hourly blood sugar monitoring." (PMID 37120562, 2023). "Higher ambulatory doses of insulin, low BMI, decreased glomerular filtration rate, admission to a surgical unit, treatment with secretagogues during admission, and late evaluation by the Endocrinology Department were associated with severe hypoglycemia." (PMID 38044455, 2023). "Hypoglycemia-associated autonomic failure (HAAF) is a maladaptive response that can be caused by recurrent episodes of insulin-induced hypoglycemia (RH) wherein there are impaired glucose sensing mechanisms in the brain and the glucose counterregulatory response (CRR)." (PMID 37108651, 2023). "The serum insulin levels peaked in 10–20 min after its intranasal administration, then remained slightly elevated for approximately 1 h and returned to mean values 1.5–2 h after nebulization with an insignificant risk of hypoglycemia mainly in a fasting state." (PMID 36834685, 2023). "A multi-national study disclosed that insulin users exhibited higher risk of hypoglycemia than oGLD combination users, suggesting that insulin use could indirectly modulate their frailty risk." (PMID 37196125, 2023). "Several antibiotics have been documented to cause hypoglycemic episodes; the use of antibiotics along with insulin or sulfonylureas might further increase the risk of hypoglycemia." (PMID 37700268, 2023). "Changes in metabolism, such as decreased insulin sensitivity and impaired counter‐regulatory hormones’ responses, may contribute to a higher risk of hypoglycemia in this population." (PMID 40496787, 2023). "VIL-INS showed reduced HbA1c and frequency and dosage of insulin with a low risk of hypoglycemia." (PMID 38021574, 2023). "However, reduced dosage flexibility and increased risk of hypoglycemia are of concern with premixed insulin." (PMID 36650625, 2023).
Hypoglycemia (continued). "Hypoglycemia in CF patients might be linked to factors such as delayed initial insulin secretion, liver disease, malnutrition, gastrointestinal complications, and dysfunctions related to the incretin hormones." (PMID 38136081, 2023). "However, these neuroendocrine pathways are easily overwhelmed by the use of insulin analogues and/or secretagogues, leading to inadvertent hypoglycemia and the clinical syndrome of hypoglycemia-associated autonomic failure (HAAF)." (PMID 38298268, 2023). "SGLT2 inhibitors work by blocking glucose reabsorption at SGLT2 channels in the proximal convoluted tubule of the kidney and therefore lower glucose independently of insulin, avoiding hypoglycemia and weight gain, which are associated with insulin or its secretagogues." (PMID 37441367, 2023). "The risk for hypoglycemia is low unless they are used in combination with insulin or sulfonylureas." (PMID 37298274, 2023). "The results showed that using 5 units of IV insulin reduced the risk of posttreatment hypoglycemia compared to 10 units of IV insulin (OR 0.307, 95% CI 0.117 to 0.806), which preserved potassium lowering effects (potassium difference -0.096 mmol/L, 95%CI -0.250 to 0.058, p 0.221)." (PMID 36371171, 2022). "Patients at high risk of hypoglycemia may benefit from a combination of metformin-SGLT2 inhibitors, as the risk of hypoglycemia of the latter is low compared to treatment with insulin and sulfonylurea derivatives." (PMID 35885680, 2022). "Exercise can improve insulin sensitivity, decrease insulin requirements, decrease microvascular complications, and reduce cardiovascular disease in patients with T1D, although it can be associated with exercise-induced hypoglycemia." (PMID 35601019, 2022). "When used with a sulfonylurea or with insulin, a lower dose of the sulfonylurea or insulin may be considered to reduce the risk of hypoglycemia." (PMID 36552050, 2022). "Another potential DTP of importance among Syrian refugees is labeled as “safety”; including prescribing both insulin and sulfonylurea, which increases the risk of hypoglycemia, and dispensing metformin for patients with GFR < 30 mL/min that would increase the risk of lactic acidosis." (PMID 35742447, 2022). "Too high an insulin dose may cause a counter-regulatory response to prevent hypoglycaemia, thus inducing ITT becomes a compound test of insulin sensitivity and counter-regulatory response." (PMID 36713454, 2022). "Fifth, the portosystemic and intrahepatic shunting, reduced insulin extraction, and decreased sulfonylurea metabolism due to cirrhosis may raise the risk of hypoglycemia in patients taking insulin or insulin secretagogues." (PMID 36687427, 2022). "It is well recognized that sulfonylurea or insulin can cause hypoglycemia." (PMID 35915395, 2022). "The signs and symptoms of insulin overdose are those of hypoglycemia caused by any factor." (PMID 35324747, 2022). "First, nocturnal and early morning hypoglycemia in patients with BN may be associated with excessive or delayed insulin secretion after binge eating or FBH." (PMID 36303193, 2022). "Despite these limited but encouraging results, it should be taken into consideration that carbohydrate restriction associated to KDs may increase the risk of hypoglycemia in these patients, especially in those treated with insulin and/or insulin secretagogues." (PMID 36339405, 2022). "The increased frequency observed in T1DM can be explained by the renal and pancreatic effects of SGLT2-inhibitors that are emphasized in patients in add-on combination therapy with insulin, since to minimize the risk of hypoglycemia it is necessary to decrease the insulin dose." (PMID 35337085, 2022). "Rapid-acting insulin analogs (insulin lispro, aspart, and glulisine) may then be added as needed because they can rapidly decrease blood glucose levels while carrying a lower risk of postprandial hypoglycemia than regular short–acting insulin." (PMID 35252271, 2022).
Hypoglycemia (continued). "However, intensive insulin therapy increases the risk for hypoglycemia onset three-fold in these patients, which can be further exacerbated with regular exercise." (PMID 36083870, 2022). "However, patients, especially elderly patients, did not comprehensively understand insulin therapy, so increased insulin units would increase the risk of hypoglycemia or other severe events, such as ketoacidosis." (PMID 35250851, 2022). "One mechanism, for instance, could be suboptimal nutrition in the uterus, predisposing the individual to fetal hypoglycemia, limiting insulin secretion, and, consequently, increasing protein breakdown and decreasing its accumulation." (PMID 35626762, 2022). "Hypoglycemia represents the commonest acute complication of antidiabetic treatment, especially when medications like insulin or sulfonylureas are used, and may also be associated with increased cardiovascular risk." (PMID 36011166, 2022). "However, considering long-term insulin injection, it will cause body edema, hypoglycemia and other adverse reactions." (PMID 36405706, 2022). "Insulin is associated with weight gain and the risk of hypoglycemia." (PMID 34922811, 2022). "In a man with chronic hypoglycemia-plasma glucose (PG), 2.1 mmol/L with undetectable serum insulin, less than 7.2 pmol/L on admission-the cause of the hypoglycemia was HMW-IGF-II in the serum secreted by an intrathoracic benign pleural solitary fibrous tumor (size: 15 × 17 × 12 cm)." (PMID 37908273, 2022). "The identification of mutations within INS shows an association with neonatal hypoglycemia." (PMID 36573710, 2022). "As an alternative, three studies suggested that twice a day IDegAsp administration could lower the risk of hypoglycemia based on a lower dose, which could be reduced to 80% of the basal insulin dose according to two studies." (PMID 35784980, 2022). "In addition, serious risk factors must be considered in managing the complex association of insulin and fasting, as patients receiving high insulin doses are at greater risk for hypoglycemia during IF." (PMID 36235648, 2022). "Several medications, such as insulin and sulfonylureas, have been associated with an increased risk of AF, possibly through hypoglycemia and glycemic fluctuation, and stimulation of the sympathetic nervous system is associated with an increased incidence of AF." (PMID 35765074, 2022). "The risk of hypoglycemia is also high when delivering the initial dose of insulin." (PMID 36072265, 2022). "The risk of severe hypoglycaemia during pregnancy can be reduced while maintaining good glycaemic control by the use of a multifactorial clinical approach that includes careful timing of meals and adequate dosing of insulin analogues." (PMID 36432552, 2022). "Therefore, combined administration of 2-O-M with insulin not only exerts a better glucose-lowering effect, minimizing the risk of hypoglycemia, but also decreases the secretion of endogenous insulin to protect β cell function." (PMID 35502441, 2022). "Women also have a higher risk of experiencing severe hypoglycemia with insulin therapy." (PMID 35883660, 2022). "A total score ≥ 2 points or met criteria at least one of the following: age > 60 years old, pretreatment blood glucose ≤ 100 mg/dL (≤ 5.6 mmol/L), or pretreatment potassium > 6 mmol/L indicated a high risk for posttreatment hypoglycemia in hyperkalemic patients treated with IV insulin and glucose." (PMID 36371171, 2022). "For example, if an ultra-rapid-acting insulin tends to cause postprandial hypoglycaemia, an insulin with a slower onset of action may avoid this." (PMID 36194250, 2022). "As exercise training may reduce the blood glucose in patients with T2DM, there is a risk of hypoglycemia, especially if the patients are treated with insulin." (PMID 35162066, 2022). "Insulin-induced hypoglycemia reached the same level in control and mutated mice." (PMID 36180454, 2022).